PVT1 (Pvt1 oncogene)
Diseases named in the same sentence as PVT1 in open-access papers (continued):
Sharing a sentence is not in itself a finding about the gene and the disease.
cancer (continued). "Previously, we reported that PVT1 epigenetically maintains FOXM1 protein level, which is protein characterized by its role in inducing sensitization to antitumor drugs in cancer cells." (PMID 38098223, 2024). "In the 1980s, PVT1 was discovered and named as a MYC activator, and it has presented a tumor-promoting effect in a variety of malignant tumors." (PMID 36869031, 2023). "PVT1, a well-known oncogenic lncRNA, is usually coexpressed with MYC (MYC proto-oncogene) and is vital for increasing the expression of MYC in cancer." (PMID 37255541, 2023). "EZH2 interacts with several lncRs including PVT1 to modulate EMT and cancer stemness related to drug resistance." (PMID 36552560, 2022). "Prior work found that in 98% of cancers with MYC copy number increases, the amplified region includes the PVT1 gene." (PMID 36139061, 2022). "Emerging research has revealed that PVT1 and SNHG15 play important roles in the progression of various cancers, including KIRC." (PMID 36052236, 2022). "Effects of PVT1 expression on PFS were also grade and stage dependent with an increased HR for Grade 2 (HR: 2.753, P = 0.0256) and cancer Stage 4 (HR = 2.374, P = 0.007)." (PMID 35820706, 2022). "Among these, LINC00824 (PVT1), which is adjacent to c-MYC gene and frequently upregulated in many cancers, was identified as a BRD4 target." (PMID 35399501, 2022). "Several lncRNAs, such as SNHG12, PVT1, and LINC00672, were shown to function crucially in carcinomas." (PMID 35341001, 2022). "Among them, lncRNAs PVT1, H19, and UCA1 were proved to involve in gemcitabine resistance in other cancers and CCA progression, suggested that our screen strategy for gemcitabine resistance-related lncRNAs were feasible." (PMID 33436545, 2021). "Specifically, the PVT1 copy number increase was found to be the critical factor for MYC, and subsequent c-Myc, elevation in MYC-driven cancers." (PMID 33499210, 2021). "Previous meta-analyses have indicated that DLX6-AS1, PVT1, SNHG15 and GHET1 are related to the clinicopathological features and prognosis of various cancers." (PMID 34923990, 2021). "PVT1 and MYC are co-amplified in a variety of human tumors, and the co-amplification results in MYC stabilization and proliferation of cancer cells." (PMID 33435206, 2021). "A study reported that PVT1 is involved in the EMT and distant metastasis of cancer cells as follows." (PMID 34336125, 2021). "Lots of targets were the same between the two cancer types, like GNL2 at 1p34.3, PVT1 at 8q24, and HOXB genes at 17q21.32, indicating some common genetics shared between these two gynecologic tumors." (PMID 33815481, 2021). "The increased expression of PVT1, CYTOR, FOXD2-AS1, and CRNDE were seen in various cancers, similarly these lncRNAs were all up-regulated in G-CIMP-low suggesting their more oncogenic activity leads to poor prognosis compared to G-CIMP-high." (PMID 33926464, 2021). "This gain of both PVT1 and MYC has been shown to be essential for tumourigenesis in 8q24-amplified cancer cells." (PMID 33499210, 2021). "Consistent with other similar studies that reported MALAT1 and PVT1 were correlated with CRC nodal and/or distant metastases and different types of cancer." (PMID 34200314, 2021). "We found that there are higher number of literature for up-regulated PVT1, CCAT1 and CRNDE, suggesting that they have been mostly investigated in cancer." (PMID 32127004, 2020). "Tissue microarray analysis of primary tumors indicated a high correlation between PVT1 and MYC expression, providing strong evidence for cooperation between PVT1 and MYC in different human cancers." (PMID 32992461, 2020). "PVT1 is located at the 8q24 locus adjacent to MYC, which is highly expressed in many types of cancer and plays an important role in carcinogenesis." (PMID 32992461, 2020). "In cancer cells, knockdown of PVT1 expression inhibits the expression of cyclin D1 and CDK4, which suggests that PVT1 positively regulates the expression of cyclin D1 and CDK4." (PMID 31309249, 2019).
cancer (continued). "Along with MYC and PVT1, the CCDC26 lncRNA gene lies in the human chromosome 8q21 region that is frequently amplified in cancer." (PMID 31338324, 2019). "According to the description of the topology structure, the PVT1 promoter, MYC promoter, and the four enhancers belong to the same TAD in normal tissues, while in cancer cells, the circumstance is different." (PMID 31309249, 2019). "The proximal location between the well-established oncogene MYC and PVT1 in the 8q24 region prompted researchers to analyze whether this lncRNA may somehow regulate or be regulated by MYC, a master regulator of cell growth, proliferation, and differentiation, widely implicated in cancer." (PMID 31781490, 2019). "In squamous cell carcinoma of the head and neck, PVT1 can promote EMT and increase cancer stem cell-like properties by activating the Wnt/β-catenin pathway." (PMID 31497532, 2019). "PVT1 upregulates the expression of HIF-1α by binding to miR-199-5p and miR-186, thus further facilitating the proliferation of cancer cells." (PMID 31497532, 2019). "Interestingly, mRNA levels of these molecules decrease with PVT1 knockdown and increase with PVT1 overexpression PVT1 is implicated in DR and MDR in many cancer types, but further study is required to fully understand the pathways that mediate this PVT1-related cancer drug-resistance." (PMID 31249809, 2019). "For example, the lncRNA PVT1 has been shown to be required for increasing MYC protein stability and high expression levels in 8q24-amplified cancers." (PMID 29466962, 2018). "As expected, our microarray profiles identified several lncRNAs, which were aberrantly expressed in human cancer, such as LOC100190940, LOC100506178, H19, PVT1, VPS9D1-AS1, Linc00520, Linc00675, GNG12-AS1 CDKN2B-AS1, and CCAT1." (PMID 29523145, 2018). "PVT1, one such oncogenic lncRNA, is a large locus located 57 kb downstream of MYC in the well-known cancer-related region 8q24." (PMID 30046623, 2018). "The lncRNAs such as MALAT1, GAS5, ANRIL, PVT1, CCAT2 and HOTAIR etc. were found to be novel promising biomarkers to predict a poor prognosis in human cancers." (PMID 28594897, 2017). "Two studies comprising 403 cancer patients reported the HRs for RFS, and the results shown that PVT1 overexpression was significantly related with poor RFS (HR = 1.74, 95% CI: 1.01–2.47)." (PMID 29348896, 2017). "TCGA cohorts revealed that among all cancer types, CCRCC showed the strongest up-regulation of PVT1, and the highest level of PVT1 correlated with poor clinical outcome." (PMID 29254209, 2017). "To analyze in detail the PVT1 amplification, we used the HNSCC cancer data set provided by The Cancer Genome Atlas (TCGA)." (PMID 29262850, 2017). "Among all onco-lncRNAs, there were only 9 DELs dysregulated in all the four cancer types: CTD-2047H16.2, CTD-2517M22.14, CTD-2574D22.3, FGF14-AS2, PVT1, RP11-196G18.22, RP11-346D14.1, RP11-498C9.4 and RP11-510N19.5." (PMID 28389669, 2017). "Because PVT1 is less abundant in across normal tissue and possesses a protective role for MYC protein, PVT1 appears to be a promising target for 8q24 amplified cancers." (PMID 29113413, 2017). "PVT1 RNA and MYC protein expression correlate in several primary human tumors, and a direct relationship between copy number of PVT1 and MYC copy-increase has been found in more than 98% of human cancers." (PMID 29165379, 2017). "Specifically, PVT-1 occupies a unique cell context within the 8q24.21 region and was demonstrated to be required for the high MYC protein levels in 8q24-amplified human cancer cells." (PMID 27813492, 2016). "PVT1 lncRNA and MYC protein expressions are correlated in primary human tumors, and the copy number of PVT1 was increased in more than 98% of cancers that also showed an increase of MYC copies." (PMID 26602695, 2016).
cancer (continued). "Among all cancers types, kidney renal clear cell carcinoma (KIRC) showed the strongest upregulation of PVT1 and increased levels of both MYC and PVT1 correlated with the clinical outcome." (PMID 27366943, 2016). "Thus, we sought to better define the role of PVT1 in cervical carcinogenesis by examining PVT1 expression patterns in cervical cancer tumors and cell lines and the functional effects of this lncRNA on cancer-related processes such as proliferation, cell motility, apoptosis, and chemoresistance." (PMID 27232880, 2016). "Some well-known cancer related lncRNAs such as H19, PVT1 and XIST all regulated the ‘negative regulation of cell proliferation’ process across different cancers." (PMID 27580177, 2016). "These include some known cancer biomarkers such as PCGs CDK1 and TGFBR3, as well lncRNAs PVT1 and ADAMTS9-AS2." (PMID 26812883, 2016). "Recent findings revealed that the PVT1 lncRNA controls MYC protein stability and they both cooperate to promote cell proliferation in cancer." (PMID 27366943, 2016). "Previous reports have shown that PVT1 stabilizes MYC protein levels, promoting cell proliferation in cancer." (PMID 27366943, 2016). "More importantly, a recent report has also highlighted the involvement of PVT1 in regulating MYC, which has been firmly established to play a role in cancer." (PMID 26545364, 2015). "According to this study, PVT1 controls levels of MYC through regulation of the protein stability and they both cooperate to promote cell proliferation in cancer." (PMID 25883951, 2015). "PVT1 is an exceptionally interesting lncRNA, both in its ability to physically interact with and regulate MYC and its pivotal roles in many cancers, making it an attractive therapeutic target to combat different cancers." (PMID 27077133, 2015). "Co-amplification of PVT1 and MIR1204 with MYC has been reported in several types of cancers, and their oncogenic roles have been also suggested." (PMID 23716474, 2013). "Additionally, studies have also reported that hypoxia-related lncRNAs such as PVT1, DANCR, and HIFCAR facilitate the stabilization and transcriptional network of HIF-1α to facilitate cancer progression." (PMID 40004471, 2025). "We used RT-PCR primers specific for CircPVT1 to demonstrate that it was significantly more abundant in cancer cell lines with MYC/PVT1 genomic rearrangements (MYC/PVT1 gain + PVT1 translocation, COLO-320DM, SK-PN-DW, and D458) compared to MYC/PVT1 neutral cell lines (U2OS, BxPC-3, and DU145)." (PMID 40027648, 2025). "Furthermore, another study demonstrated that the lncRNA PVT1 interacts with TME components to promote apoptosis resistance and enhance cancer cell survival 151–153." (PMID 41335135, 2025). "Based on these observations, we hypothesized that PVT1 genomic rearrangements, including amplifications and translocations, significantly contribute to the aggressive nature of MYC+ cancers." (PMID 40027648, 2025). "However, we have previously shown that in 98% of MYC+ cancers, MYC is co-amplified with PVT1, a long non-coding RNA (lncRNA) gene located ~30kb downstream of MYC8." (PMID 40027648, 2025). "Even though true tumor-specific expression of PVT1 was not given, the PVT1 protein was 15.9-fold enriched in cancer samples compared to the controls." (PMID 38731892, 2024). "PVT1 targeted the expression of miR-1207-3P, which, in turn, regulated the production of Hepatocyte Nuclear Factor 1-β (HNF1-B), promoting angiogenesis and spreading of cancer." (PMID 40176927, 2024). "It has been identified that lncRNA GJA9‐MYCBP and PVT1 are aberrantly expressed in different human cancers, but it is not clear how these lncRNAs contribute to ALL or serve as a diagnostic biomarker in this kind of cancer." (PMID 38994720, 2024). "Overall, most frequently found lncRNA fusions in cancers involved MALAT1 and PVT1 parts." (PMID 38919532, 2024).
cancer (continued). "Notably, the silencing of PVT1 reversed the multi-drug resistance in CRC, considering that mTOR is one of the primary factors in cancer drug resistance." (PMID 37280524, 2023). "Proliferation of cancer cells can be boosted by the simultaneous expression of MYC and PVT1." (PMID 36624401, 2023). "Furthermore, PVT1 can act as a sponge to competitively bind miR-128-3p and elevate FOXQ1, inducing epithelial-mesenchymal transformation of cancer cells." (PMID 37263709, 2023). "The results showed that GSTA2 levels were downregulated in the cancer tissues of patients with the PVT1 rs2278176 CT/TT genotype, but not adjacent tissues." (PMID 35433465, 2022). "Combining these results and the findings suggesting direct interaction of PVT1 and CypB, we were interested in whether the connection between PVT1 and CypB play roles in STAT3 function in cancer cells." (PMID 36266267, 2022). "We then detected the PVT1 levels in CRC cancer tissues with CC and TT genotypes, and the results showed that the expression levels of PVT1 in patients with different PVT1 rs2278176 genotypes were not significantly altered." (PMID 35433465, 2022). "MALAT1 rs3200401 and PVT1 rs13255292 SNPs were assessed with different types of cancer, but not yet extensively investigated in CRC." (PMID 34200314, 2021). "For instance, PVT1 promotes cancer progression in gallbladder cancer; NORAD promotes cell proliferation, invasion, and migration and inhibits apoptosis in lung cancer; and MFI2-AS1 promotes cancer progression and metastasis in hepatocellular carcinoma." (PMID 33737947, 2021). "Although it is known that PVT1 regulates functions of miRNA to promote cell proliferation and invasion in cancer, it is still not clear how I/R injury, and interference with mitochondrial fission/fusion processes are directed by PVT1 and miR-21-5p." (PMID 34131106, 2021). "Although PVT1 has been shown to regulate HIF1α transcriptionally by binding with KAT2A and play oncogenic roles in cancers, we demonstrated that PVT1 could bind HIF2α and stabilize HIF2α protein, thus promote tumorigenesis and angiogenesis." (PMID 34321604, 2021). "PVT1 increases Myc protein levels in 8q24-gain cancers, while either Myc or PVT1 fails to measurably promote cancer." (PMID 34527584, 2021). "PVT1, a non-protein coding gene, has been demonstrated to play an oncogenic role in various cancers." (PMID 33801373, 2021). "Further studies are required to elucidate PVT1’s role in TNBC, and other cancers." (PMID 33801373, 2021). "PVT1 depletion can induce apoptotic cell death of cancer cells, whereas MYC silencing does not affect cell death, suggesting different mechanisms of PVT1 and MYC function in different cancers." (PMID 33435206, 2021). "PVT1 is highly expressed in cancer tissues compared with non-cancerous tissues and in cancer cell lines." (PMID 34527584, 2021). "This suggests different mechanisms of PVT1 and MYC cooperation in different cancers." (PMID 32117705, 2020). "Ultimately, we successfully established the PVT1/miR-20b/CCND1 cancer-related ceRNA network, which was not only significantly associated with the prognosis of PC patients but also played key roles in the progression of PC." (PMID 33008376, 2020). "While most studies have indicated only one miRNA being targeted by PVT1 in most cancers, this should not be taken as the norm." (PMID 32117705, 2020). "Our findings of PVT1 elevation in plasma cells of MM compared to MGUS suggest a role of PVT1 in the pathogenesis of malignant clonal plasma cells and the progression from precancerous stages to cancer." (PMID 32992461, 2020).
cancer (continued). "Since PVT1/ miR-519d-3p and HIF-1A participate in regulating PDAC cancer progression and glycolysis, we researched whether PVT1/ miR-519d-3p functions through regulating HIF-1A." (PMID 32201527, 2020). "Accordingly, lncRNA PVT1 plays pivotal roles in a variety of human cancers, such as ovarian carcinoma, pancreatic carcinoma, and non-small cell lung carcinoma." (PMID 33126409, 2020). "Among them, many well-known cancer relevant genes such as MALAT1 and PVT1 were included." (PMID 33318305, 2020). "A large number of articles have identified that lncRNAs such as lncRNA PVT1, lncRNA HULC, and lncRNA CRNDE are closely related to the initiation and progression of various cancers and could serve as prognostic biomarkers." (PMID 32493915, 2020). "Indeed, a number of genes contained in the cMYC locus have been involved in the pathogenesis or progression of different cancers, including BOP1, PVT1, FAM84B or POU5F1P1." (PMID 32932846, 2020). "The CRISPRi-PVT1 did not induce an increase in MYC transcription in some cell types, and not all cancers examined had mutations of the PVT1 promoter." (PMID 32117705, 2020). "As radiation is a primary treatment for NPC, and PVT1 suppresses radiosensitivity in NPC, we reasoned that the molecular mechanism by which PVT1 regulates cancer progression may be closely related to NPC radiosensitivity." (PMID 31320749, 2020). "Indeed, PVT1 inhibition can induce cell apoptosis, even in PVT1-overexpressing cells, whereas MYC silencing does not produce the same effect, suggesting different mechanisms of PVT1 and MYC cooperation in different cancers." (PMID 33142861, 2020). "Although lncRNA Pvt1 mechanism in cancer cells is clear, how lncRNA Pvt1 controls function and differentiation of MDSC is not well-known." (PMID 33133086, 2020). "Besides PVT1, the CASC11 noncoding gene is highly expressed in GC tissues and cell lines, and its knockdown inhibits cancer progression." (PMID 32150871, 2020). "To summarize, although mechanisms of PVT1 acted were not the same in various cancers, many similarities were still existed." (PMID 30083911, 2019). "Currently, the mechanism of action of PVT1 in cancer and the interaction mechanism with MYC are not completely clear; however, in-depth studies of PVT1 can contribute to the development of new therapeutic targets." (PMID 31309249, 2019). "Moreover, PVT1 could engage in multiple signaling pathways or act as competitive endogenous RNA (ceRNA) to affect the biological function of cancer cells via interacting with miRNAs and target genes, indicating a novel perspective for therapeutic strategies of human cancers." (PMID 31632195, 2019). "The list of subtype-specific DM lncRNAs from the three subtypes contained previously defined epigenetically altered lncRNAs from other cancer types, for example, we observed the oncogenic lncRNAs LINC00312, PVT1, and TCL6, which are differentially methylated in at least one of the three subtypes." (PMID 30642353, 2019). "The nonprotein coding gene locus plasmacytoma variant translocation 1 (PVT1) is located at 8q24 and is dysregulated in different cancers." (PMID 31766781, 2019). "Tissue microarray analysis of 8 primary tumors (lung, colon, rectum, stomach, esophagus, liver, kidney, and mammary gland) indicated a high correlation between PVT1 and c-Myc expression, providing strong evidence for the cooperation of PVT1 and MYC in different human cancers." (PMID 31309249, 2019). "Although the increasing number of mechanisms of action for PVT1 and its interaction with MYC in cancer are being discovered, there is no application for PVT1 in clinical treatment to date, and only one clinical trial on PVT1 is recruiting subjects." (PMID 31309249, 2019). "Consistently, PVT1 is overexpressed in cancer cells compared to normal non-tumorigenic epithelial cells." (PMID 31249809, 2019).